FGF21 (fibroblast growth factor 21)
Diseases named in the same sentence as FGF21 in open-access papers (continued):
Sharing a sentence is not in itself a finding about the gene and the disease.
Obesity (continued). "At baseline, the BDNF level was similar between the preoperative DM (n = 30) (17.1 ± 7.7 ng/ml) and non-DM (n = 48) (17.0 ± 6.9 ng/ml) patients with obesity, but FGF21 was significantly higher in the DM patients (201.5 ± 204.3 versus 107.6 ± 63.8 pg/ml)." (PMID 32210348, 2020). "Collectively, endogenous FGF21-signaling is an interesting therapeutic target, as it appears sufficient to prevent obesity in the absence of UCP1." (PMID 32005798, 2020). "Consistent with a protective role, endogenous FGF21 serum concentration may be elevated by up to 10–20-fold in patients with NAFLD, NASH, obesity, type 2 diabetes, chronic kidney disease, diabetic nephropathy, atherosclerosis, or coronary heart disease." (PMID 33381084, 2020). "In conclusion, diabetic patients with obesity had higher FGF21 and similar BDNF levels compared to non-diabetic obese patients." (PMID 32210348, 2020). "To date, there have been no reports detailing the full transcriptional response to FGF21 in any primate species, nor any attempts to infer gene expression networks active during FGF21 treatment in an obesity model." (PMID 32350364, 2020). "In conclusion, these data suggest that FGF21 molecules such as LY2405319 might be candidate drugs for the treatment of atherosclerosis in patients with DM and obesity." (PMID 32957703, 2020). "Additionally, GLP-1 can stimulate the hepatic expression of fibroblast growth factor-21 (FGF-21), which plays a critical role in metabolic regulation, with beneficial effects on insulin resistance, hyperglycemia, hyperlipidemia, and obesity." (PMID 32679813, 2020). "These transcriptome analyses suggested that Mafg inhibition reinstated a healthy, less inflammatory expression profile in livers of obese mice, exemplified by trends toward increased serum fibroblast growth factor 21 (FGF21) levels, a hepatokine beneficial in the context of obesity in mice." (PMID 32005828, 2020). "In a recently published paper, we concluded that FGF21 might be a novel predicting factor of CMD development in patients with psoriasis, especially with severe form or concomitant obesity." (PMID 32605214, 2020). "In this observational study, we investigated the relationship of FGF21, adiponectin, and FAR with IHTG percent in a clinically well-characterized pediatric cohort of pubertal children with obesity participating in a short-term (6-month) lifestyle intervention program." (PMID 33071964, 2020). "Collectively, this study characterizes the effects of endogenous FGF21 that acts as master regulator to protect from diet-induced obesity in the absence of UCP1." (PMID 32005798, 2020). "Fibroblast growth factor 21 (FGF21) is a promising antiobesityagent, but its effects on melanocortin obesity are unknown." (PMID 33659800, 2020). "Outcome measures included plasma lipids, amino acids, glucose, serum FGF21, and other biomarkers related to energy metabolism, including adipose tissue gene expression and plasma SCD activity indices in healthy women with overweight and obesity." (PMID 32160926, 2020). "Not obviously affecting energy expenditure, food intake or body temperature, the thermogenic potential of FGF21-controlled browning of iWAT may be weak as compared to BAT, but the metabolic impact appears to be powerful for preventing obesity." (PMID 32005798, 2020). "Interestingly, miRNA-34a suppresses the process of browning under conditions of obesity, in part via its regulation of SIRT1 and FGF-21." (PMID 31281288, 2019). "Anti-obesity and anti-diabetic effects have been reported in some, but not all, human trials of FGF21 analogues." (PMID 31370146, 2019). "The present evidence suggests that low-protein diets can stimulate energy expenditure via FGF21 and WAT browning and could be used as a dietary strategy for obesity treatment." (PMID 31178938, 2019).
Obesity (continued). "In conclusion, in this exploratory study, weight loss after 12 months either through CER or IER did not result in a change in FGF-21 level in healthy subjects with overweight or obesity." (PMID 31817052, 2019). "Our results suggested that the serum levels of FGF21 may be related to obesity or hyperglycemia in patients with PTC, and that FGF21 promotes tumor progression via upregulation of the FGFR signaling axis, including phosphorylation of AKT and ERK." (PMID 31408968, 2019). "Importantly, Fgf21 methylation status can be modulated in early life, and once established it persists into adulthood and exerts long-term effects on the magnitude of gene expression response to environmental cues, which may account in part for the attenuation of diet-induced obesity." (PMID 29434210, 2018). "To further address the pathophysiological role of elevated FGF21 in obesity, we raised FGF21 concentration in FGF21 knockout (FGF21KO) mice to a level equivalent to those occurring in diet-induced obesity and then monitored the metabolic changes under this condition." (PMID 29348470, 2018). "Additionally, the inhibition of the mitochondrial respiratory function by metformin results in the upregulation of fibroblast growth factor 21 (FGF21), which also possesses anti-obesity and anti-diabetes effects." (PMID 29467658, 2018). "Then, inflammation in adipose tissue, a common condition in obesity, diabetes, and HIV lipodystrophy, may contribute to impaired FGF21 responsiveness in adipocytes." (PMID 29661866, 2018). "In obesity, but not in the lean state, there is resistance to FGF21, because of downregulation of its receptor machinery, including β-klotho protein levels." (PMID 30116482, 2018). "Although elevated endogenous FGF21 fails to induce the desired physiologic effects of lipid and glucose homeostasis during obesity, pharmacological administration of FGF21 appears to exert beneficial actions to improve metabolic parameters in mice." (PMID 28466020, 2017). "FGF-21 is not specific to MD and has been shown to increase in many other conditions, including obesity, diabetes, fatty liver disease, and metabolic syndrome." (PMID 28825656, 2017). "Of note, levels of FGF21 are significantly increased in patients with T2D and non-alcoholic fatty liver disease and positively correlate with BMI in humans, indicating obesity as a possible FGF21-resistant state." (PMID 28974990, 2017). "FEN also inhibited the elevation in hepatic and adipose Fgf21 induced by obesity and impaired glucose homeostasis in Leprdb mice, demonstrating that the effects of FEN on Fgf21 gene expression are common to both diet- and genetically-induced obesity." (PMID 28256636, 2017). "Importantly, Fgf21 expression and serum levels were similar in Alb-cre-Ptp1b−/− and fl/fl mice with HFD-induced obesity, but FEN strongly decreased FGF21 in both groups." (PMID 28256636, 2017). "Fibroblast growth factor-21 (FGF-21) improves insulin sensitivity and lipid metabolism in obese or diabetic animal models and has been proposed as a potential therapeutic agent for treating T2DM, obesity, and their related complications." (PMID 28225059, 2017). "To investigate the relationship between FEN and leptin signalling and determine effects on FGF21 levels in non-diet-induced obesity, we used the Leprdb genetic mouse model." (PMID 28256636, 2017). "A recent study suggested that adipose tissue inflammation in obesity could lead to the repression of beta-Klotho expression by TNF alpha and impaired FGF21 in adipocytes." (PMID 25850006, 2015). "Moreover, studies have suggested decreased hepatic/adipose tissue expression levels of βKlotho in human obesity and DIO rodents resulting in decreased FGF21 signalling in target organs." (PMID 24498293, 2014).
Obesity (continued). "In animal studies, overexpression or pharmacological administration of FGF21 ameliorates fatty liver, obesity and type 2 diabetes without a hyperproliferative side-effect characteristic of paracrine and autocrine-acting heparan sulfate-binding FGFs." (PMID 23590285, 2013). "Interestingly, administration of either FGF21 or FGF19 has beneficial effects on lipid metabolism and improves hepatic steatosis in animal models with diet-induced obesity." (PMID 23840612, 2013). "Large epidemiological studies of human populations have shown that significantly enhanced levels of FGF21 accompany obesity, impaired glucose tolerance, type 2 diabetes, and non-alcoholic fatty liver disease (NAFLD)." (PMID 23981342, 2013). "FGF21 plasma levels are increased in type 2 diabetes, obesity, nonalcoholic fatty liver disease (NAFLD) and dyslipidemia, but injection of FGF21 in animal models of insulin resistance has been shown to improve this condition." (PMID 23999826, 2013). "FGF21 has been recognized as a hormonal regulator that reduces plasma glucose and TAG concentrations, enhances insulin sensitivity, and inhibits development of obesity and hepatosteatosis." (PMID 22394566, 2012). "In vivo treatment with FGF21 results in amelioration of glucose and regulates lipid metabolism in both murine and nonhuman primate models of diabetes and obesity." (PMID 21525989, 2011). "In vivo, treatment with FGF-21 resulted in amelioration of glucose and lipid parameters in both murine and nonhuman primate models of diabetes and obesity." (PMID 21206918, 2010). "Remarkably, the increased expression of ChREBPβ and FGF21 in the liver is what most effectively distinguishes metabolically healthy individuals from those with unhealthy states, regardless of the presence of obesity." (PMID 41373582, 2025). "This suggests that FGF21 could serve as an independent predictor of T2DM and obesity." (PMID 39764565, 2025). "Furthermore, serum biomarkers reflective of mitochondrial function, namely FGF21 and mitochondrial open reading frame of 12S rRNA-c (MOTS-c), were analysed in a cohort of adolescents with severe obesity ± MASLD, in which the prevalence of maternal obesity was high." (PMID 40496439, 2025). "However, FGF21 analogs have shown little or no efficacy in improving body weight, blood glucose, and HbA1c in people with obesity and T2D." (PMID 40171198, 2025). "The ongoing phase 2b SYMMETRY trial evaluated the efficacy of efruxifermin, a fibroblast growth factor 21 (FGF-21) analog, in patients with biopsy-confirmed, compensated cirrhosis (Child-Pugh A) due to MASH.The trial enrolled 181 adults, 80% of whom had both obesity and T2DM." (PMID 41104308, 2025). "According to pregestational nutritional status, first- and second-trimester AFABP concentrations were higher in women with obesity than in normal-weight and overweight women, and third-trimester FGF21 concentrations were lower in women with obesity than in normal-weight women." (PMID 39698038, 2024). "However, as obesity progresses, reduced FGF21 signaling may result from the downregulation of KLB, leading to “FGF21 resistance”." (PMID 39599611, 2024). "However, no change in circulating FGF21 levels was observed after 8 weeks of endurance T in men with obesity but not T2DM or after 10 weeks of either resistance or aerobic T in women with overweight and T2DM." (PMID 39640300, 2024). "Unlike other studies, we interpreted this result as FGF21 may not be a marker of metabolically healthy or unhealthy obesity, however, more comprehensive studies with larger samples should be performed to support this hypothesis." (PMID 39008201, 2024). "Moreover, 11-10-8 LNP-based FGF21 mRNA therapy exhibited superior weight-reducing and lipid-lowering effects compared to the MC3 LNP-based mRNA therapy, resulting in a significant alleviation of obesity and fatty liver in a diet-induced obese mouse model." (PMID 38409275, 2024).
Obesity (continued). "The administration of recombinant FGF21 protein to mice fed an ob/ob, db/db, or high-fat diet (HFD), or obese Zucker diabetic fatty (ZDF) rats, has been shown to result in a significant reduction in obesity, lower blood glucose and triglyceride levels, and improved insulin sensitivity." (PMID 39902162, 2024). "However, it is important to note that the standard chow-fed lean mice, which did not exhibit obvious obesity-related metabolic inflammation and dysfunction, were used in this study, and the wild-type controls were not from the littermates of Fgf21 KO mice." (PMID 38321233, 2024). "This is probably similar to fibroblast growth factor 21 (FGF21) and growth differentiation factor 15 (GDF15), whose endogenous expression and circulating levels are elevated in obese humans and mice despite their beneficial effects on obesity and related metabolic complications." (PMID 39436790, 2024). "Furthermore, we discovered that decreasing levels of circulating FGF-21 and GDF-15 were associated with greater weight loss at one year regardless of the type of anti-obesity therapies." (PMID 37436597, 2023). "However, waist circumference correlates with total FGF-21 serum levels but does not correlate with intact FGF-21, suggesting that functional FGF-21 does not necessarily relate with obesity and metabolic features." (PMID 37409233, 2023). "Our results showing that intact FGF-21 levels are not correlated with waist circumference, Vitamin D and HDL-c, differently from total serum FGF-21 levels, suggests the fact that functional FGF-21 does not necessarily relate with obesity and metabolic features." (PMID 37409233, 2023). "However, our cross-sectional study showed for the first time that FGF21 and leptin were able to discriminate the metabolic state in children without and with obesity, respectively." (PMID 38138907, 2023). "Thus,FGF21-treated obese male mice exert reduced BW regardlessof the type of obesity (hereditary, HFD- or SFD-inducedobesity), and FGF21-treated obese female mice – only atalimentaryform of obesity." (PMID 37469453, 2023). "Paradoxically, higher FGF21 level was observed in obesity-related diseases including nonalcoholic fatty liver disease, coronary heart disease, type 2 diabetes mellitus (T2DM) and metabolic syndrome, which may be resulted from FGF21 resistance." (PMID 37009852, 2023). "Notably, although most activation of BAT thermogenesis requires the help of Ucp1, endogenous FGF21 can prevent obesity by browning WAT in the absence of Ucp1 in mice." (PMID 36594101, 2023). "In addition, exercise, as a potent inducer of FGF21, can regulate energy status and myosin synthesis in skeletal muscle through mTOR and AMP-activated protein kinase (AMPK) to ameliorate the occurrence of obesity and muscle development." (PMID 38069273, 2023). "Moreover, several FGF21 analogs, such as Pegbelfermin (Bristol-Myers Squibb), LY2405319 (Eli Lilly), and PF05231023 (Pfizer), have passed Phase I/II trials and were reported to be generally well tolerated and effective in treating obesity or diabetes." (PMID 37218012, 2023). "In female Ay mice withgenetically induced obesity, unlike males, FGF21 did not affectbody weight, blood insulin levels, or POMC expression in thehypothalamus, but increased food intake and liver weight andmodified the expression of metabolic genes in the liver and inwhite adipose tissue." (PMID 35434487, 2022). "Three proteins, C1QTNF1, FGF-21 and CST3, reflecting dyslipidemia and kidney disease, displayed a higher association with HF in patients who did not undergo weight-loss-surgery and maintained with obesity." (PMID 35945262, 2022). "Circulating FGF21 levels were correlated with BMI and insulin resistance (HOMA-IR), but not with serum levels of estrogens or free androgens, demonstrating FGF21 not to be associated with PCOS, but with obesity and IR." (PMID 36289764, 2022).
Obesity (continued). "Finally, our study did not include any grade III obesity patients, but the trend in our sample suggests that FGF21 and RBM3 would increase accordingly." (PMID 35207221, 2022). "However, patients with obesity with progression to NASH fail to adapt to pathologic stresses leading to hepatic mitochondrial dysfunction with higher proton leak, oxidative stress, and inflammation, even under further elevated FGF21 levels." (PMID 35663311, 2022). "Therefore, they concluded that FGF-21 was not a useful marker for metabolic abnormalities such as insulin resistance, dyslipidemia, obesity and hypertension in women with PCOS." (PMID 35574015, 2022). "These strategies have shown promising results in treating dyslipidemia but not hyperglycemia, suggesting that a combination of FGF21 with other glucose-lowering agents could be an option for treating obesity-related metabolic complications." (PMID 35909571, 2022). "Despite increased serum levels of FGF21 in obesity patients, no metabolic benefits were observed." (PMID 35983184, 2022). "The present study suggests that TSK is mainly involved in hyperinsulinemia, as a marker of insulin resistance and the level of FGF21, a hepatic stress-induced hepatokine, rather than obesity and the level of adiponectin, an adipose-derived factor adipokine, in a general population." (PMID 35323680, 2022). "Therefore, circulating FGF-21 levels were significantly higher in nondiabetic subjects with obesity when compared to lean healthy control subjects, indicating a potential resistance to FGF-21 in these subjects." (PMID 35883694, 2022). "We further investigated whether FGF21 is required for melatonin-mediated attenuation of obesity and insulin resistance by pair-feeding FGF21−/− mice an HFD with or without melatonin for 8 weeks." (PMID 36207302, 2022). "However, whether dysregulation of FGF21 and GDF15 in obesity affects tolerance during IAV or SARS-CoV-2 infection remains to be experimentally confirmed." (PMID 34777390, 2021). "Furthermore, it is reported that obesity-induced elevated miRNA-34a could suppress sirtuin 1 (SIRT1) function and adipocyte FGF21, while downregulation of miRNA-34a could improve hepatic FGF21 signaling to alleviate adiposity." (PMID 34349728, 2021). "However, the benefit of augmented FGF21 and GDF15 treatment in reducing risk for severe IAV and SARS-CoV-2 infection in obesity has not yet been explored." (PMID 34777390, 2021). "Thus, the purpose of this study was to analyze FGF21 protein levels in PLWH and to examine its relationship with metabolic changes such as insulin resistance, lipid profile disorders and inflammatory factors, paying special attention to the obesity variable." (PMID 34019585, 2021). "Individuals with metabolic disease (i.e. diabetes, NAFLD and obesity) display increased circulating levels of FGF-21; this has been attributed to a resistance to this hormone, and the administration of pharmacological doses of exogenous FGF-21 would overcome the resistance." (PMID 33877366, 2021). "Along these lines, FGF21 expression is induced by the integrated stress response (ISR) pathway, an evolutionarily conserved adaptive system of eukaryotic cells for the restoration of cellular homeostasis in response to diverse stimuli including aging, obesity, and nutritional stressors." (PMID 33762965, 2021). "Therefore, combinatorial treatment with FGF21 and AMPK activators may have enhanced therapeutic efficacy as an anti-obesity treatment because of these divergent signaling routes." (PMID 34066631, 2021). "Concomitantly, resistance to release of exercise-inducible factors might also be involved, potentially elucidating, at least in part, why FGF21, follistatin, irisin, and METRNL are frequently increased in patients with obesity and T2DM, even in basal conditions." (PMID 32604889, 2020).